RNU7-67P (RNA, U7 small nuclear 67 pseudogene)
Synonyms: U7.67
Gene: Small nuclear RNA gene on chromosome 8 (101,307,367 to 101,307,428, forward strand). Ensembl gene ENSG00000239115.
Homologues: Orthologues: macaque U7 (89% identical). Paralogues in human: RNU7-35P (89% identical), RNU7-171P (87% identical), RNU7-60P (87% identical), RNU7-80P (87% identical), RNU7-11P (85% identical), RNU7-137P (85% identical), RNU7-13P (85% identical), RNU7-22P (85% identical), RNU7-34P (85% identical), RNU7-52P (85% identical), RNU7-6P (85% identical), RNU7-7P (85% identical), and 141 more.